USP1 (ubiquitin specific peptidase 1)
Diseases named in the same sentence as USP1 in open-access papers (continued):
Sharing a sentence is not in itself a finding about the gene and the disease.
diffuse large B-cell lymphoma (3 papers, 2024 to 2025). "Consistent with our results, the study in diffuse large B-cell lymphoma (DLBCL) showed that USP1 directly interacted with and stabilized MAX (a MYC-binding protein) through deubiquitination, then promoted the transcription of MYC target genes." (PMID 39513905, 2024). "Notably, a specific USP1 inhibitor, Pimozide, a US FDA-approved antipsychotic drug, exhibits potent anticancer effects in preclinical models of AML, T cell leukemia, and diffuse large B cell lymphoma, with minimal toxicity." (PMID 41146039, 2025). "A recent study found that the USP1 inhibitor pimozide inhibited the deubiquitination of MAX/MYC proteins by USP1, induced apoptosis, autophagy, and cell cycle arrest in tumor cells, and improved rituximab treatment of diffuse large B-cell lymphoma resistance." (PMID 39253578, 2024).
HCMV infection (3 papers, 2023 to 2026). "Our previous studies demonstrated a requirement for USP1 activity in the establishment of latent CMV infection." (PMID 41533576, 2026). "These will be important targets to investigate going forward in understanding the role of UL138 and its interaction with USP1 in modulating DDR pathways in the context of CMV infection." (PMID 41533576, 2026). "As UAF1 is also important for activities of USP12 and USP46, this finding suggests differential roles for UAF1–USP complexes in CMV infection beyond activating USP1." (PMID 41533576, 2026). "Sustainment of pSTAT1 by USP12 may be coordinated with that of USP1 in the context of HCMV infection or they may function distinctly under different contexts." (PMID 37289831, 2023). "Future work will investigate UL138’s regulation of UAF1/USP1 as a potential mechanism to mitigate cell stress during a sustained innate immune response or if the proteins involved in the DNA damage response have an independent role in HCMV infection." (PMID 37289831, 2023). "We did not directly test the role of the UAF1 scaffold in HCMV infection, as its knockdown is likely to have pleiotropic effects due to the combined loss of USP1, USP12, and USP46 activity." (PMID 37289831, 2023). "Therefore, USP1 also mediates deubiquitination of these proteins in WT CMV infection." (PMID 41533576, 2026). "Here, we show that USP1, PCNA, and FANCD2, were relocalized to sites of vDNA synthesis during productive CMV infection in primary fibroblasts." (PMID 41533576, 2026). "Given the reported roles of USP1 in stabilizing TBK1 and of UL138 in inducing STING for degradation outside the context of infection, we analyzed total and phosphorylated levels of TBK1 and STING during HCMV infection." (PMID 37289831, 2023). "We find that sustained pSTAT1 during HCMV infection depends on both UL138 and USP1." (PMID 37289831, 2023).
pancreas tumor (3 papers, 2022 to 2025). "In this study, we found USP1 elevated in pancreatic cancer and USP1 expression inversely correlated with overall survival." (PMID 39814232, 2025). "A BCAAS-rich diet promotes pancreatic cancer development through USP1-mediated BCAT2 stabilization, and BCAAS intake is positively correlated with pancreatic cancer risk." (PMID 40438606, 2025). "Although USP1 has been reported to participate in numerous cancer types, the specific role in pancreatic cancer remains largely unclear." (PMID 39814232, 2025). "Then, USP1 inhibitor SJB3-019A was used to detect if it synergized with cisplatin in pancreatic cancer treatment." (PMID 39814232, 2025). "Taken together, genetic depletion or pharmacologic inhibition of USP1 suppresses pancreatic tumor growth in vivo, suggesting that targeting USP1 provides a promising therapeutic strategy in PDAC therapy." (PMID 39814232, 2025). "Targeting USP1 provides a potential strategy for autophagy-activated pancreatic cancer." (PMID 39814232, 2025). "Targeting USP1 using a selective inhibitor I-138 may provide an effective strategy for chemotherapy treatment and combating drug resistance in autophagy-activated pancreatic cancer." (PMID 39814232, 2025). "More importantly, USP1 inhibition recedes cell proliferation and clone formation in PDAC cells and attenuates pancreas tumor growth in an orthotopic transplanted mice model." (PMID 35663242, 2022). "Here, we investigated the role of USP1 in autophagy and revealed that ablation of USP1 suppressed autophagy in PDAC, which not only provides a new mechanism for autophagy activation in pancreatic cancer but also identifies USP1 as a therapy target for pancreatic cancer." (PMID 39814232, 2025).
acute myeloid leukemia (2 papers, 2021 to 2023). Acute myeloid leukemia (AML) is a group of neoplasms arising from precursor cells committed to the myeloid cell-line differentiation. "It was reported that pimozide inhibited the viability of acute myeloid leukemia (AML) cells by promoting the degradation of the USP1 substrate ID1." (PMID 36352191, 2023).
Hashimoto thyroiditis (2 papers, 2024 to 2025). An autoimmune disorder caused by the production of autoantibodies against thyroid tissue. "Studies demonstrate that Ubiquitin-specific peptidase 1 (USP1) drives Hashimoto’s thyroiditis (HT) progression through deubiquitination-mediated stabilization of NLRP3 and promotion of its transcription, which significantly enhances inflammasome-mediated pyroptosis." (PMID 40832584, 2025).
Hepatic fibrosis (2 papers, 2023 to 2024). The presence of excessive fibrous connective tissue in the liver. "Although studies have shown that USP1 regulates hepatic fibrosis and glucose metabolism, this is the first study on USP1 in relation to adipogenesis." (PMID 38012162, 2023). "Ubiquitin-specific peptidase 1 (USP1) interacts with SNAIL to deubiquitinate it and stabilize its expression, which in turn increases the expression of CXCL1 in liver tissues and promotes hepatic fibrosis." (PMID 39113708, 2024).
metabolic disorders (2 papers, 2023). "As USP1 inhibition downregulates C/EBPβ protein levels, we asserted for the first time that USP1 inhibition is a potential therapeutic target against metabolic diseases, including obesity." (PMID 38012162, 2023). "Moreover, we suggest the potential of the USP1 inhibitor ML323 in the treatment of obesity-related metabolic disorders and further study by ML323 is needed for clinical application." (PMID 38012162, 2023). "In this study, we demonstrated that USP1 has the potential to modulate metabolic diseases." (PMID 38012162, 2023). "However, there are few studies relating metabolic diseases or obesity to the function of USP1." (PMID 38012162, 2023). "Several studies have utilized chemical blockers to assess the roles of USP in metabolic disorders; e.g., GSK2643953A for USP20 in obesity, ML323 and SJB-043 for USP1 in β-cell damage, ML364 for USP2 in hypothalamic function, and HBX41108 for USP7 in diabetic foot ulcers." (PMID 36834633, 2023). "Taken together, we suggest that USP1 plays an important role in adipogenesis by regulating C/EBPβ ubiquitination, and USP1-specific inhibitor ML323 is a potential treatment option and further study by ML323 is needed for clinical application for metabolic disorders." (PMID 38012162, 2023).
T-cell leukemia (2 papers, 2022 to 2025). A malignant disease of the T-lymphocytes in the bone marrow, thymus, and/or blood. "Pimozide, an inhibitor of USP1, results in the arrest of adult T-cell leukemia cells in the G1 phase, leading to the accumulation of p21 and p27 and reduction in the protein levels of cyclin D2, cyclin E, CDK2, CDK4, and CDK6." (PMID 36357365, 2022).
acute lymphoblastic leukemia (1 paper, 2023). Leukemia with an acute onset, characterized by the presence of lymphoblasts in the bone marrow and the peripheral blood. "In T-cell acute lymphoblastic leukemia (T-ALL), ALKBH5 could enhance the expression of ubiquitin-specific protease 1 (USP1) by stabilizing its transcripts." (PMID 36810281, 2023).
B-cell acute lymphoblastic leukemia (1 paper, 2021). A neoplasm of lymphoblasts committed to the B-cell lineage, typically composed of small to medium-sized blast cells. "However, the role of USP1 in B-cell acute lymphoblastic leukemia (B-ALL) remains largely undefined." (PMID 33390793, 2021).
Burkitt lymphoma (1 paper, 2022). A rare form of malignant mature B-cell non-Hodgkin lymphoma. "This study reports for the first time elevated expression of USP1 protein in both Burkitt lymphoma and mantle cell lymphoma." (PMID 35432321, 2022). "To answer this question, we analyzed the expression of USP1 by western blotting in Ramos and several other Burkitt lymphoma (BL) and non-BL cell lines." (PMID 35432321, 2022).
colon adenocarcinoma (1 paper, 2019). "The expression level of USP1 was firstly analyzed by Gene Expression Profiling Interactive Analysis (GEPIA), and the results showed that USP1 expression was significantly higher in colon adenocarcinoma compared with that of controls (p < 0.05)." (PMID 31921663, 2019).
diabetic nephropathy (1 paper, 2023). "In contrast, USP1, 5, 9X, 14, 15, 22, 36, and 48 modulate the progression of diabetic nephropathy, neuropathy, and/or retinopathy." (PMID 36834633, 2023).
diabetic retinopathy (1 paper, 2023). "In contrast to USP48, there are reports that two USPs, namely USP1 and 14, are deteriorative in diabetic retinopathy." (PMID 36834633, 2023). "USP1 in retinal vascular endothelial cells and USP14 in Müller cells are complicating factors for diabetic retinopathy, whereas USP28 in retinal pigment epithelial cells suppresses the progression of retinopathy." (PMID 36834633, 2023). "Moreover, the Usp1 shRNA conserved VEGF-induced permeabilization of vessels, implying that USP1 contributes to diabetic retinopathy." (PMID 36834633, 2023).
endometriosis (1 paper, 2025). The growth of functional endometrial tissue in anatomic sites outside the uterine body. "The p-values indicate that four genes (DIP2C, DNMT1, RRP1, and USP1) are significantly differentially hypomethylated in the endometriosis group compared to the control group." (PMID 39858463, 2025). "The four hypomethylated genes in endometriosis are RRP1, DIPC2, USP1, and DNMT1." (PMID 39858463, 2025).
Epstein-Barr virus infection (1 paper, 2017). An infection that is caused by Epstein-Barr virus. "BPLF1 promotes Epstein-Barr virus infection and pathogenesis by mimicking USP1, deubiquitinating PCNA to disrupt the recruitment of DNA polymerases such as polη, and thus impeding DNA damage repair." (PMID 29091922, 2017).
Ewing sarcoma (1 paper, 2024). A small round cell tumor that lacks morphologic, immunohistochemical, and electron microscopic evidence of neuroectodermal differentiation. "A pharmacological inhibitor of USP1 was able to activate cdc42 and inhibit Ewing sarcoma growth." (PMID 38323120, 2024). "We also found that USP1 inhibits cdc42, enhances EWS-FLI1 transcriptional output, and stimulates Ewing sarcoma growth." (PMID 38323120, 2024). "We demonstrate that a USP1 inhibitor, ML323, is able to activate cdc42 and inhibit growth in Ewing sarcoma." (PMID 38323120, 2024). "We also find that USP1 inhibits cdc42, increases EWS-FLI1 transcriptional output, and simulates Ewing sarcoma growth." (PMID 38323120, 2024). "Upon further investigation of the mechanism of differential chemotherapy sensitivity of the CD133high and CD133low populations, we found that USP1 is a transcriptional activation target of EWS-FLI1 and is a key determinant of chemotherapy sensitivity in Ewing sarcoma." (PMID 38323120, 2024).
Hepatic steatosis (1 paper, 2023). Steatosis is a term used to denote lipid accumulation within hepatocytes. "Furthermore, administration of the USP1-specific inhibitor ML323 to mice fed an HFD effectively reduced fat mass, improved hepatic steatosis, and improved insulin sensitivity." (PMID 38012162, 2023).
inflammatory bowel disease (1 paper, 2023). A spectrum of small and large bowel inflammatory diseases of unknown etiology. "Co-localisation analyses across genetic effects on DNA methylation and 56 human traits identify 1520 co-localisations across 1325 unique CpGs and 34 phenotypes, including in disease-relevant genes, such as USP1 and DOCK7 (total cholesterol levels), and ICOSLG (inflammatory bowel disease)." (PMID 37525248, 2023).
influenza (1 paper, 2025). An acute viral infection of the respiratory tract, occurring in isolated cases, in epidemics, or in pandemics; it is caused by serologically different strains of viruses (influenzaviruses) designated A, B, and C, has a 3-day incubation period, and usually lasts for 3 to 10 days. "After infecting the sh-control, sh-usp1, and WT cells with four subtypes of influenza strains (H1 N1, H3 N2, BY, BV) at MOI = 0.01, samples of the supernatants were collected at 12 h, 24 h, 36 h, 48 h, and 60 h post-infection for the TCID50 assay." (PMID 40369332, 2025). "In summary, we reached a preliminary determination that USP1 is an effective target gene for the establishment of high-yield, genetically engineered MDCK cell lines for influenza vaccine production." (PMID 40369332, 2025). "Does the USP1 gene have an antiviral function in the regulation of the influenza virus response in MDCK cells, and could it therefore serve as an effective target gene to promote influenza vaccine yield?" (PMID 40369332, 2025).
lung adenocarcinoma (1 paper, 2025). A carcinoma that arises from the lung and is characterized by the presence of malignant glandular epithelial cells. "Interrogation of the Human Protein Atlas (HPA) revealed differential overexpression of USP1 protein in lung adenocarcinoma specimens compared to adjacent normal parenchyma, establishing its tumor-specific expression pattern." (PMID 40136409, 2025). "To dissect USP1’s functional interactome, we employed Pearson correlation analysis to assess the relationship between USP1 and proliferation/apoptosis and migration-related markers (Ki-67, PCNA, Bcl-2, N-cadherin) using mRNA expression data from TCGA lung adenocarcinoma samples." (PMID 40136409, 2025).
lung squamous cell carcinoma (1 paper, 2023). "For example, USP1 deubiquitinates FANCD2/FANCI or PCNA to prevent the recruitment of interstrand crosslink repair proteins and translesion DNA polymerase to inhibit DNA repair; USP7 regulates lung squamous cell carcinoma cell proliferation through MEK/ERK signaling by deubiquitinates the Raf-1." (PMID 37107644, 2023).
mantle cell lymphoma (1 paper, 2022). Mantle cell lymphoma is a rare form of malignant non-Hodgkin lymphoma affecting B lymphocytes in the lymph nodes in a region called the ``mantle zone''. "Similar elevated expression of USP1 was found in human B cells derived from mantle cell lymphoma." (PMID 35432321, 2022).
mesothelioma (1 paper, 2026). A usually malignant and aggressive neoplasm of the mesothelium which is often associated with exposure to asbestos. "Together, these findings identify USP1 as a context-dependent therapeutic vulnerability in BAP1-deficient mesothelioma and support a working model in which USP1-dependent maintenance of FANCD2 function becomes critical in the absence of functional BAP1." (PMID 42069682, 2026). "In this study, we investigated the context-dependent interplay between BAP1 and ubiquitin-specific protease 1 (USP1) in mesothelioma cells, focusing on their roles in regulating FANCD2, cell proliferation, and DNA damage responses." (PMID 42069682, 2026). "Although both BAP1 and USP1 were capable of deubiquitinating FANCD2 in vitro, USP1 suppression in mesothelioma cells did not provide clear biochemical evidence of altered FANCD2 ubiquitination." (PMID 42069682, 2026).
osseous tumors (1 paper, 2023). "USP1 and USP6 inhibit osteogenesis in osseous tumors have been shown in previous studies." (PMID 36859264, 2023).
portal hypertension (1 paper, 2025). Increased blood pressure in the portal venous system. "Clinical analysis shows USP1 and KIF11 are overexpressed in HCC patients with portal hypertension and strongly correlate." (PMID 40546347, 2025). "Inhibition of USP1 with ML323 reduces KIF11 levels and suppresses tumor progression in vivo, identifying USP1 as a potential therapeutic target for HCC, particularly in patients with portal hypertension." (PMID 40546347, 2025).
stomach adenocarcinoma (1 paper, 2022). "For instance, Ubiquitin-Specific Protease 1 (USP1) over-expression has been found in stomach adenocarcinoma samples as compared to normal tissue, with higher USP1 expression being associated with shorter overall survival." (PMID 36578788, 2022).
T cell lymphoma (1 paper, 2023). "Subsequently, we detected the expression of USP1, MAX and MYC in DLBCL, Burkitt and T cell lymphoma cell lines by using western blotting analysis, and found that the protein levels of USP1, MAX and MYC were high in RL-4RH cells." (PMID 36352191, 2023).